CXCR4 (C-X-C motif chemokine receptor 4)
Diseases named in the same sentence as CXCR4 in open-access papers (continued):
Sharing a sentence is not in itself a finding about the gene and the disease.
infection (continued). "HIV is usually R5-tropic (uses CCR5) during the early stages of infection, but the virus may later switch to using either only CXCR4 (X4-tropic) or both CCR5 and CXCR4 (dual-tropic)." (PMID 39062756, 2024). "Among patients without a post-operative infection, there was an increase in monocyte IL-1β (p = 0.0141) and a reduction in CXCR4 (p = 0.004) in pre-operative samples." (PMID 38655251, 2024). "Compared to patients who did not have any post-operative infection, patients who developed an infection had an increase in monocyte count (p = 0.0037) and CD4+ lymphocyte IL-7R (p < 0.0001) and a decrease in monocyte CD80 (p = 0.0279) and CXCR4 expression (p = 0.0220)." (PMID 38655251, 2024). "The most common transmitted form is R5-tropic, and as infection progresses, the R5-tropic virus may change tropism to X4-tropic through acquisition of dual tropism to both CCR5 and CXCR4." (PMID 38256260, 2024). "In the absence of infection, gp120 can induce activation and stimulate the expression of collagen I in HSCs through its interaction with CXCR4, which is present on HSCs, thereby triggering profibrogenic effects." (PMID 38920978, 2024). "HIV-1 enters target cells by binding its envelope glycoprotein gp120 to the CD4 receptor and/or co-receptors such as C-C chemokine receptor type 5 (CCR5; R5) and C-X-C chemokine receptor type 4 (CXCR4; X4), and R5-tropic viruses predominate during the early stages of infection." (PMID 39339960, 2024). "This bias may have resulted in our lack of identification of host factors previously determined to be required for HIV-1NL4-3 infection, such as CD4 or CXCR4." (PMID 38835488, 2024). "At the polyclonal level, where homozygous and heterozygous edits exist, it was likely that the decrease in CXCR4 expression was enough to reduce syncytia formation, but not enough to completely block infection." (PMID 38835488, 2024). "A distinct shift was observed in the cell population based on GFP expression upon infection of CCR5+ GHOST cells, while there was no observable shift in the cell population upon infection of CXCR4+ GHOST cells." (PMID 39772167, 2024). "By contrast, no productive infection of the macrophage targets was observed after engulfment of T cells infected with non-M-tropic CXCR4-using viruses, even though these infected T cells were efficiently engulfed by macrophages." (PMID 38400063, 2024). "Cell fusions of syncytia formation are more possible for the CD4+ T-cells upon infection by the CXCR4-tropic HIV strains but not for cells that do not support productive infection of the replicating virus particles, such as the stem-progenitor cells." (PMID 39810915, 2024). "Here, we used the CXCR4-tropic strain NL4-3 which does not result in productive infection of macrophages." (PMID 39575258, 2024). "Importantly, these Th17 cells are primary target cells for HIV, expressing HIV coreceptors (CD4, α4β7, CCR5, and CXCR4), and thus play an important role in disseminating HIV during the acute phase of infection." (PMID 39352750, 2024). "The results showed that three different surface markers, CD10, CD64, and CXCR4, significantly differentiate between the presence and absence of infection in patients with febrile illnesses." (PMID 36900096, 2023). "Twelve genes were upregulated in common for CXCR4- and CCR5-tropic infection." (PMID 38156317, 2023). "Infection was carried out with a HIV GKO (HIV_LTR-GFP-EF1α-mKO2) dual-reporter vector pseudotyped with three different envelopes, as follows: VSV-G for amphotropic viral entry, and natural HIV envelopes LAI for CXCR4 tropism, and BaL for CCR5 tropism." (PMID 38067117, 2023). "Plerixafor (AMD3100) is a small molecule inhibitor of CXCR4, which suppresses infection of HIV selectivity toward X4-tropic virus rather than dual-tropic." (PMID 36647730, 2023).
infection (continued). "The mechanisms triggering the human immunodeficiency virus type I (HIV-1) to switch the coreceptor usage from CCR5 to CXCR4 during the course of infection are not entirely understood." (PMID 38127856, 2023). "For example, HIV is known to alter the composition and function of EVs, leading to the secretion of infection-promoting host proteins such as virus receptors CCR5 and CXCR4, metalloprotease ADAM17 and other proinflammatory factors, and host restrictive factors such as APOBEC3G and TRIM5α." (PMID 37396389, 2023). "Even if SCs are not primarily infected by HIV (infection has not been described in vitro), they express chemokine receptor CXCR4, a receptor for HIV-1 gp120." (PMID 35887383, 2022). "Furthermore, this technology can also be extended to other infection systems using other viruses like those mediated by a GPCR, as in the case of the CCR5 and CXCR4, members of the chemokine receptor family, during an HIV-1 infection." (PMID 35260793, 2022). "Infection of 2D organoid dissociates with the CXCR4 tropic HIV-1 HxB2-luciferase reporter virus (HxB2) was not supported." (PMID 35458559, 2022). "In contrast, the cluster 4-like cells expressed lower levels of CXCR4; this level is presumably sufficient to support productive infection but not viral-induced killing, as previously suggested." (PMID 35784348, 2022). "We also tested the effects of BMS-986158 on the expression of HIV-1 co-receptors and found that BMS-986158 did not significantly affect either the CXCR4 or CCR5 receptors, indicating that BMS-986158 does not increase the risk of infection by reactivated HIV-1." (PMID 35337136, 2022). "Approximately half of the amplified full-length single envelope-encoding clones had no significant activity for infection of cells expressing high levels of CD4 and CCR5 or CXCR4." (PMID 35727047, 2022). "In vivo, this was due to preferential selection of CXCR4low cells for infection, followed by further downregulation of CXCR4, whereas, in vitro, we only observed a selection for CXCR4low cells without a further downregulation of CXCR4." (PMID 33910003, 2021). "Infection with HIV is almost always mediated by interactions between the HIV envelope protein, gp120, the CD4 receptor and a co-receptor, generally the chemokine receptors CCR5 or CXCR4." (PMID 34429135, 2021). "Although we did observe a decrease in the expression of the inhibitory marker PD-1 and an increase in the expression of the homing markers CXCR4 and CCR7 on MuV-specific CD8+ T cells over time, it is difficult to interpret the exact role of these markers in the memory phase after an acute infection." (PMID 34960178, 2021). "Infection with CXCR4- or dual-tropic HIV isolates is possible, but such events represent a small minority of transmission due to multiple layers of restriction on CXCR4-tropic viruses in the mucosa." (PMID 34099693, 2021). "To this end, we repeated infection assays of CD4TL with RES or SENS viruses in the presence of P2G, a CXCL12 variant that binds CXCR4 with comparable affinity compared to CXCL12 but does not internalize the receptor." (PMID 33872329, 2021). "Cervical epithelial cells do not possess the receptors such as CD4+ and CXCR4/CCR5 for HIV-1 entry, and hence these cells are not susceptible for direct infection." (PMID 34835072, 2021). "This combinatorial approach may more completely prevent infection with the variety of HIV-1 strains within a patient, as well as prevent selective pressure on CXCR4-utilizing viruses." (PMID 35126374, 2021). "Gp120 triggers WAVE2 phosphorylation through both CXCR4 and CCR5, acting through early Gαi independent and late Gαi dependent mechanisms, and inhibition of Arp2/3 activity significantly attenuated HIV-1 nuclear migration and infection of CD4 + T cells." (PMID 34429135, 2021). "CXCR4 is a cytokine receptor used by HIV during cell attachment and infection." (PMID 34834337, 2021).
infection (continued). "AMD3451 inhibited infection with clinical HIV-1 isolates or a variety of R5, R5/X4, and X4 strains of HIV-1 and HIV-2 at an IC50 ranging from 1.2 to 26.5 μM in various T cell lines, CCR5- or CXCR4-transfected cells, PBMCs, and monocytes/macrophages." (PMID 35126374, 2021). "In addition to stimulated PBMCs, we also demonstrated infection in trans of FACS sorted CD4+ T lymphocyte subsets expressing co-receptors CCR5 and CXCR4." (PMID 33816339, 2021). "As expected, knockout of CXCR4 drastically decreased the number of HIV-1 infected cells compared to the NT control, whereas Cul3 knockout correlated with a robust increase of HIV-1 infected cells, as measured by flow cytometry 72 h post infection." (PMID 32882949, 2020). "Unlike wild-type HIV-1, infection with Vpu-S52,56D and Vpu-S52,56N viruses did not result in a significant loss of PEX2, PEX7, PEX11B, or PEX13 in HeLa-CD4/CXCR4/CCR5 cells, macrophages, or T cells." (PMID 32127461, 2020). "Dual-infection, however, is likely a rare event as it pertains solely to X4-tropic viruses which occur in only 50% of patients at late-stage disease and only a fraction of the EBV-infected B cells express the requisite surface receptors CD4 and CXCR4." (PMID 32576602, 2020). "TZM-bl cells were used as these are a HeLa cell derivative engineered to express high levels of HIV-1 receptor and coreceptor (CD4 and CXCR4, respectively) and contain β-galactosidase and luciferase regulated by the HIV-1 LTR promoter to quantitate infection (27, –, 29)." (PMID 32371599, 2020). "Under conditions of infection with WT V. vulnificus, HT-29 cells upregulated KLF2, KLF4, and KLF6 and downregulated NLRP3, TLR4, and CXCR4, suggesting that the MARTX toxin interrupts inflammatory responses, NF-κB signaling, and mitogen-activated protein kinase (MAPK) signaling in infected cells." (PMID 32817457, 2020). "We worked with a prototypic HIV-1 that uses CD4 and CCR5 cell-surface coreceptor to enter cells and is typical at the early stages of infection (isolate BaL) and a prototypic HIV-1 that uses CD4 and CXCR4 cell-surface coreceptor that often evolves at the late stages of infection (isolate LAI.04)." (PMID 31827089, 2019). "After a starting boost, the replication of CXCR4-tropic clones in MDM subsequently diminished reaching a status of abortive infection, while the replication of CCR5-tropic clones tended to increase, reaching a plateau after 10 days of infection." (PMID 31234437, 2019). "However, 8–10 years after post-infection, HIV-1 switches to a CXCR4 tropism in approximately 40–50% of HIV-1 infected patients." (PMID 31477581, 2019). "Considering that CXCL12 is the ligand that interacts with CXCR4 and CXCR7, these findings suggested that during a HP infection, CXCL12 regulates the homing B cell lymphocytes to gastric mucosa, and further promotes the abnormal growth of B lymphocytes through CXCL12/CXCR4 or CXCL12/CXCR7 signaling." (PMID 30999581, 2019). "Over again, confirmation was performed after infection with CCR5 or CXCR4 tropic HIV, and as expected, cells from the donor were not infected with R5 strains but with X4 trophic." (PMID 31531340, 2019). "Infection of these cells with wildtype HIV-1LAI demonstrates lower infection as compared to the controls, although this effect is not as extreme as for CXCR4 KO (31-fold decreased infection for CXCR4-KO lines in orange, 3-fold for TLR2-KO lines in green)." (PMID 30520725, 2018). "To verify whether the CXCR4 P191A mediated inhibition effect is specific to X4-tropic HIV-1 strains, we subsequently tested R5-tropic strain HIV-1YU2 infection in screened cells by luciferase reporter and p24 ELISA assays." (PMID 29872154, 2018). "One possible mechanism for reduced numbers and function of these cells could be direct infection and destruction by HIV-1 itself, at least among those Vδ2 expressing CD4 and chemokine receptors CCR5 and CXCR4 or α4β7." (PMID 30219039, 2018).
infection (continued). "Therefore, the examination of CXCR4 modification is of importance in order to block infection by both CCR5- and CXCR4-utilizing viruses." (PMID 30619107, 2018). "In some patients, the CXCR4 imaging revealed severe allograft pyelonephritis rather than infection of the native kidney." (PMID 30631428, 2018). "However, over the course of infection, the preference of HIV for CCR5 co-receptor usage changes to CXCR4 in up to half of infected individuals, and these CXCR4-utilizing strains exhibit a broader tropism for different T-cell subpopulations." (PMID 29677122, 2018). "The antibodies targeting this region block the infection of a CCR5-tropic HIV-1 strain without affecting a CXCR4-tropic strain." (PMID 28484468, 2017). "The reporter cell line TZM-bl, expresses CD4, CXCR4 and CCR5 receptors; thus, its expression of these receptors is similar to that on the HIV-1 target cell, CD4+ T cell, and is suitable for evaluating infection by R5, R4, or dual R5 and R4 HIV-1 viruses (SF162, R5; DH12, dual R5 and R4)." (PMID 29226013, 2017). "For example, CXCR4 use, which often evolves late in infection, does not favor transmission and is therefore lost when a virus transmits to a new host." (PMID 29056936, 2017). "In addition, Immunokine® (OXO Chemie, Thailand), an oxidized derivative of the α-toxin extracted from Naja siamensis venom, has been shown to inhibit infection of lymphocytes by HIV through the chemokine receptors CCR5 and CXCR4." (PMID 28074089, 2017). "The preferential infection of CCR6+ Th17 cells may be attributable to the higher expression of the viral receptors CD4, CXCR4, and α4β7 compared with CCR6− Th17 cells resulting in enhanced HIV envelope binding." (PMID 28509877, 2017). "There have been reports suggesting the possible infection and transmission of infection by epithelial cells even though they do not express CD4 and have undetectable or low expression of the co-receptors CCR5and CXCR4." (PMID 27998285, 2016). "The numbers of macrophages and mast cells, degranulated or not, were also found to be in the same range in Cxcr4+/1013 and wt mice, but not significantly increased upon infection in any of the two models." (PMID 27111140, 2016). "The two viral strains CXCR4 and CCR5-tropic HIV showed differential infection dynamics." (PMID 27242797, 2016). "However, since CXCR4 expression on GC B cells was unchanged upon LCMV infection, we surmise that the overall increased expression of the chemokine receptor upon infection most likely occurred in extrafollicular B cells." (PMID 27994594, 2016). "However, an additional mechanism may be the direct infection of these cells as productive HIV infection of γδ T cells within peripheral blood mononuclear cells (PBMC) as well as infection of γδ T cell clones by the CXCR4-tropic laboratory clone HIVLAI has been reported." (PMID 26473478, 2015). "Once infection is established, HIV-1 can use CXCR4 as an alternative receptor for entry." (PMID 26481100, 2015). "Unlike primate lentiviruses, SRLVs do not use CD4, CCR5, and CXCR4 molecules as receptors/coreceptors for target cell infection." (PMID 29061947, 2015). "These experiments support the theory that N-glycan g15 is partly blocking CXCR4-specific infection and that the V3 loop best-fit for making contact to CXCR4 is a sequence lacking the g15 N-glycosylation site N6N7T8." (PMID 25785610, 2015). "CXCR4 transcription significantly increased in the liver of VHSV-infected fish compared to levels observed in liver obtained from control animals, but only after 5 days of infection." (PMID 25338079, 2014). "The decreased surface expression of CD4, CXCR4, and CCR5 observed with ISD treatment may be an important factor in the blockade of de novo infection." (PMID 24827152, 2014).
infection (continued). "In contrast to all other HIV-1 T/F viruses that use either CCR5 and/or CXCR4 coreceptors for entry, the T/F virus ZP6248 established the clinical infection most likely used the coreceptor GPR15 and the unique V3 crown GPEK in ZP6248 play a critical role in the GPR15 tropism." (PMID 24897520, 2014). "We conclude that a viral population able to use CCR8 and unable to infect CCR5 or CXCR4-positive cells, may exist in some HIV-2 infected individuals during an undefined time period, in the course of the asymptomatic stage of infection." (PMID 25421818, 2014). "The functionality of this CXCR4 mimetic peptide was demonstrated by its ability to discriminate between gp120 from X4- and R5-tropic HIV-1 in binding assays involving recombinant proteins, as well as in cellular infection assays." (PMID 24027570, 2013). "Herein we show that SerpinB2 is induced in peripheral blood mononuclear cells following infection of pigtail macaques with CCR5-utilizing (macrophage-tropic) SIVmac239, but not the rapidly pathogenic CXCR4-utilizing (T cell-tropic) SHIVmn229." (PMID 23460840, 2013). "In addition, macrophages are known to express both CCR5 and CXCR4; early investigations by using HIV-1 isolates showed HIV-1 is being adapted to use CXCR4 in addition to CCR5 expressed by both macrophages and CD4+ T cells along with infection progression." (PMID 23741458, 2013). "Excluding the 10 CRF51_01B-infected individuals from analysis, 4 (20.0%) of 20 recently-infected individuals had CXCR4-using virus compared to 21 (26.3%) of 80 individuals without evidence of recent infection (P = 0.774)." (PMID 23421710, 2013). "We hypothesized that the lack of robust and sustained replication of HIVJR-CSFΔvif following direct thymic infection could be due to limited CCR5 expression in the thymus, as <5% of thymocytes express CCR5 whereas 30–40% of thymocytes express CXCR4." (PMID 23555255, 2013). "However, viruses begin their primary infections through CCR5 receptor, and change their tropism to CXCR4, probably expand to more coreceptor-usage." (PMID 24009735, 2013). "Nine (36.0%) of 25 recently-infected individuals had CXCR4-using virus, compared to 26 (30.6%) of 85 individuals without evidence of recent infection (P = 0.631)." (PMID 23421710, 2013). "Given that blood-derived monocytes/macrophages express CD4 and CCR5, but not CXCR4, they are highly susceptible to R5 HIV-1, albeit with much lower production of infectious virus than cis infection of CD4+ T cells." (PMID 24278768, 2013). "increasing numbers of CXCR4-expressing activated naive CD4+ T cells with declining total CD4+ T cell counts, thereby providing increased numbers of activated target cells for productive infection by X4 virus." (PMID 22866173, 2012). "Infection with UV-inactivated HCMV did not alter the mRNA expression of CXCR4 or CXCR7 at any timepoint analyzed, indicating that viral gene expression is required for these findings (data not shown)." (PMID 23116176, 2012). "No statistical significance was observed between all infections in the frequency of lung CD11c+ cells expressing CXCR4." (PMID 23300813, 2012). "A significant decrease was measured in the levels of CXCR4 on BM neutrophils at 24 h post infection, accompanied with a significant reduction in SDF-1 levels in the BM as well as elevation of SDF-1 levels in the blood circulation at 24 h post infection." (PMID 23189271, 2012). "Nontoxic concentrations of Tat peptide inhibited CXCR4-mediated infection by the X4 virus HIV-1 IIIB in a concentration-dependent manner." (PMID 22319541, 2012). "All envelopes were screened for functionality by testing whether env+ pseudovirions conferred infection of HeLa TZM-bl cells, which express recombinant CD4 and CCR5 along with endogenous CXCR4." (PMID 22420378, 2012).